CDKL5 (cyclin dependent kinase like 5)
Description:
May regulate ciliogenesis.
Synonyms: STK9; EIEE2; CFAP247; DEE2; ISSX
Tractability: Small molecule: a structure with a bound ligand is known; a high-quality ligand is known; it belongs to a druggable protein family. PROTAC: ubiquitination databases record sites on it; its protein half-life has been measured; a small molecule that binds it is known.
Target class: Protein Kinase; CMGC protein kinase CDKL family; CMGC protein kinase group; Enzyme; Kinase
Chemical probes: SGC-CAF382-1 (high quality), SGC-CDKL5/GSK3-1 (high quality)
Gene: Protein-coding gene on chromosome X (18,425,583 to 18,653,629, forward strand). Ensembl gene ENSG00000008086.
Subcellular location: Nucleus; Cytoplasm, cytoskeleton, cilium basal body; Cytoplasm, cytoskeleton, microtubule organizing center, centrosome
Subcellular location (Human Protein Atlas): Nucleoplasm
Gene Ontology:
Molecular function: ATP binding; kinase activity; protein binding; protein kinase activity; protein serine/threonine kinase activity; small GTPase binding; cyclin-dependent protein serine/threonine kinase activity; protein serine kinase activity
Biological process: modulation of chemical synaptic transmission; regulation of cilium assembly; regulation of postsynapse organization; neuron migration; positive regulation of axon extension; positive regulation of dendrite morphogenesis; positive regulation of Rac protein signal transduction; regulation of dendrite development; regulation of cell cycle
Cellular component: centrosome; ciliary basal body; ciliary tip; glutamatergic synapse; nucleoplasm; nucleus; dendrite cytoplasm; dendritic growth cone; ruffle membrane
Gene-disease validity (ClinGen):
ClinGen rates the evidence that CDKL5 causes each of these diseases.
CDKL5 disorder (X-linked): Definitive. A monogenic disease that has material basis in mutation in the CDKL5 gene.
Homologues: Orthologues: dog CDKL5 (98% identical), pig CDKL5 (98% identical), rabbit CDKL5 (96% identical), rat Cdkl5 (96% identical), mouse Cdkl5 (96% identical), guinea pig CDKL5 (95% identical), chimpanzee CDKL5 (95% identical), macaque CDKL5 (95% identical), tropical clawed frog cdkl5 (72% identical), zebrafish cdkl5 (63% identical). Paralogues in human: CDKL2 (20% identical), CDKL3 (18% identical), CDK13 (17% identical), CDK12 (16% identical), CDKL1 (16% identical), CDKL4 (16% identical), CDK19 (14% identical), CDK8 (13% identical), CDK11A (13% identical), CDK11B (13% identical), CDK17 (13% identical), CDK1 (13% identical), and 14 more.
Diseases named in the same sentence as CDKL5 in open-access papers:
CDKL5 is named in the same sentence as 158 diseases in open-access papers, as found by Europe PMC text mining. Sharing a sentence is not in itself a finding about the gene and the disease. The quoted sentences say what the papers report.
epilepsy (111 papers, 2012 to 2026). A brain disorder characterized by episodes of abnormally increased neuronal discharge resulting in transient episodes of sensory or motor neurological dysfunction, or psychic dysfunction. "The CDKL5 gene encodes cyclin-dependent kinase-like 5, the loss of function of which leads to epilepsy beginning in the first months or years of life." (PMID 40650152, 2025). "Pathogenic variation in the gene CDKL5 was the third most common cause of monogenic epilepsy identified across 24 NGS studies mainly involving children." (PMID 40381056, 2025). "All patients had epilepsy and development impairment and found to carry pathogenic or likely pathogenic CDKL5 variants." (PMID 38874638, 2024). "CDKL5, involved in regulating neuronal activity and brain circuit formation, plays a significant role in epilepsy susceptibility and clinical presentation." (PMID 38874638, 2024). "A three-step epilepsy phenotype associated with CDKL5 variants has been described, consisting of early epilepsy (stage I), followed by epileptic encephalopathy (stage II), and finally late multifocal and myoclonic epilepsy (stage III)." (PMID 38612920, 2024). "The usage of GNX in children/adolescents has been recently approved for cyclin-dependent kinase-like 5 (CDKL5) deficiency, a disease characterized by epilepsy and intellectual and motor disabilities." (PMID 38427732, 2024). "On the other hand, patients with Rett phenotype together with early-onset epilepsy caused by mutations in the cyclin-dependent kinase-like 5 gene (CDKL5)." (PMID 39544232, 2024). "The TAK-935 clinical trial was focused on the conditions of epilepsy, Dravet syndrome, Lennox–Gastaut syndrome, 15q duplication syndrome, CDKL5 deficiency disease, and developmental and/or epileptic encephalopathies." (PMID 38248286, 2024). "To date, several studies have used brain organoids to study CDD-associated epilepsy, showing that CDKL5 disruption leads to hyperexcitability of glutamatergic neurons and hypersynchronous neuronal activity associated with epilepsy." (PMID 39409097, 2024). "CDKL5 deficiency disorder (CDD) results in early-onset epilepsy and lifelong cognitive and motor impairments." (PMID 37184758, 2024). "CDD represents one of the most common genetic causes of epilepsy in infants, affecting females, who are heterozygous for CDKL5 deficiency due to random X-chromosome inactivation four times more often than males." (PMID 36982627, 2023). "Pathologic mutations in cyclin-dependent kinase-like 5 cause CDKL5 deficiency disorder, a genetic syndrome associated with severe epilepsy and cognitive, motor, visual, and autonomic disturbances." (PMID 35794776, 2023). "CDKL5 deficiency disorder (CDD), a rare and severe neurodevelopmental disease caused by mutations in the X-linked CDKL5 gene, is characterized by early-onset epilepsy, intellectual disability, and autistic features." (PMID 35955854, 2022). "An early onset with an ictal sequence starting in SWS with a tonic event and spasms suggests a possible mechanism underlying the epilepsy in CDKL5 encephalopathy." (PMID 37193389, 2022). "Drug-resistant epilepsy is one of the most important features of cyclin-dependent kinase-like 5 (CDKL5) deficiency disorder." (PMID 36274176, 2022). "Epilepsy, sleep abnormalities, gastrointestinal disorders (constipation, gastroesophageal reflux and air swallowing) were more frequent in patients with CDKL5 mutations than RTT, while scoliosis and respiratory problems had a lower prevalence." (PMID 35299616, 2022).
epilepsy (continued). "The most common cause of epilepsy was genetic, including patients with findings in chromosomal microarray tests or mutations in specific genes (CDKL5, TSC2, etc.)." (PMID 36203978, 2022). "The authors present an unreported 2.5-year-old male patient with drug-resistant epilepsy who was diagnosed with a de novo mutation in the CDKL5 gene." (PMID 36553250, 2022). "Our strategic use of CDKL5-deficient cells as a biological tool to understand its complex phenotypes provides additional insight into the epilepsy field and new compounds for curative or ameliorative therapies." (PMID 33888873, 2021). "In 2019, minimum diagnostic criteria for CDD were proposed to include the presence of a pathogenic or likely pathogenic variant in CDKL5, epilepsy onset within 1 year of age, and motor and cognitive delays." (PMID 34530725, 2021). "Epilepsy before 1 year of age is present in almost all patients carrying cyclin-dependent kinase-like 5 (CDKL5) variants who are affected by epilepsy." (PMID 34440332, 2021). "It is worth noting that similar results have been described for other neurodevelopmental disorders that present with epilepsy, such as CDKL5 deficiency disorder or fragile X syndrome (FXS)." (PMID 34272258, 2021). "Another Phase II, crossover study of ataluren (NCT02758626) is ongoing for the treatment of drug-resistent epilepsy caused by Dravet syndrome and cyclin-dependent kinase-like 5 (CDKL5) deficiency." (PMID 32630050, 2020). "Based on the combined related literature and the manifestations observed, we diagnosed the three children as CDKL5-related disorders, and concluded that the de novo CDKL5 mutations are the reason for their epilepsy." (PMID 32111237, 2020). "Here, we created an artificial escape by editing DNA methylation on the promoter of CDKL5, a gene causative for an infantile epilepsy, from the silenced X-chromosomal allele in human neuronal-like cells." (PMID 31925439, 2020). "CDKL5 deficiency disorder (CDD) is characterized by epilepsy, intellectual disability, and autistic features, and CDKL5-deficient mice exhibit a constellation of behavioral phenotypes reminiscent of the human disorder." (PMID 31201320, 2019). "In RTT associated with CDKL5 mutations, epilepsy is typically manifested as an epileptic encephalopathy, with infantile spasm, multifocal and myoclonic seizures." (PMID 30929312, 2019). "The exon 2 deletion showed positive segregation with the LQTS and the mutation in the CDKL5 gene with the epilepsy in this family." (PMID 29261713, 2017). "Genetic variants in KCNQ1 and CDKL5 genes were identified in ID#1, who had family members affected by epilepsy and/or long QT syndrome." (PMID 29261713, 2017). "Epilepsy is the hallmark feature of CDKL5 disorder with almost every case having at least some seizures." (PMID 27080038, 2016).
epilepsy (continued). "Similarly, in a population-based study of children with epilepsy onset before 36 months, CDKL5 was one of the most common monogenic causes of epilepsy, accounting for 5% of all genetic diagnoses made." (PMID 40381056, 2025). "Self-reported impact of cyclin-dependent kinase-like 5 deficiency disorder on caregivers’ family, social, and professional life; financial resources; sleep; stress; and overall quality of life, according to the level of epilepsy-related burden." (PMID 40493384, 2025). "CDKL5 mutations are among the most commonly identified pathogenic findings in epilepsy gene panels." (PMID 41301530, 2025). "Furthermore, mutations within the cyclin‐dependent kinase‐like 5 (CDKL5) gene result in various neurological disorders with epilepsy, like Rett syndrome and West syndrome." (PMID 39888294, 2025). "The exact mechanisms by which CDKL5 causes severe early-onset epilepsy are poorly understood." (PMID 39409097, 2024). "In addition, our study showed that the CDKL5 genotype was more frequently associated with epilepsy, which is in accordance with other studies." (PMID 38540345, 2024). "CDKL5 deficiency disorder is one of the most common genetic forms of epilepsy." (PMID 38081835, 2023). "Sleep disorders, epilepsy, gastrointestinal problems characterize CDKL5 Deficiency Disorder (CDD)." (PMID 35299616, 2022). "The impact of CDKL5 deficiency on inhibitory neurotransmission might explain the presence of drug-resistant epilepsy and cognitive defects in CDD patients." (PMID 36613509, 2022). "Cyclin-Dependent Kinase-Like 5 (CDKL5) encephalopathy is an X-linked disorder characterized by early-onset epilepsy with intractable seizures and severe psychomotor development delay, due to pathogenic variant (single nucleotide variant or large deletion) in CDKL5 gene located on Xp22." (PMID 37193389, 2022). "Pathogenic variants in CDKL5 cause early-life epilepsy in 1 per 40,000–60,000 live births." (PMID 36274176, 2022). "Consequently, it is believed that the function of CDKL5 in the cytoplasm is closely associated with its role in the epilepsy observed in CDD." (PMID 32587608, 2020). "A report in 2013 described 86 patients with a mutation in CDKL5 with data originating from family questionnaires recorded in InterRett, and more recently, epilepsy and vagus nerve stimulation was studied in a cohort of 172 cases with a pathogenic CDKL5 mutation." (PMID 31049350, 2019). "Heterozygous female CDKL5-deficient patients show a vast clinical heterogeneity that spans from milder forms—with less severe epilepsy and less severe comorbidities—to more severe forms featuring intractable seizures and the lack of achievement of developmental milestones." (PMID 29977282, 2018). "Additionally, 75% (6/8) of mosaic pathogenic variants identified in CDKL5 were in affected males noted to have epilepsy and/or developmental delay, and 25% (2/8) were in affected females with epilepsy and developmental delay." (PMID 28837158, 2018). "While the exon 2 deletion in KCNQ1 showed complete segregation with the LQTS, it is unlikely that the CDKL5 variant was causative of the observed epilepsy, as mutations related to this gene typically occur de novo and are associated with early-onset, severe, drug-refractory epileptic encephalopathy." (PMID 29261713, 2017). "Epilepsy is the core symptom of the patients with CDKL5 mutation." (PMID 24564546, 2014). "Importantly, early-onset drug-resistant epilepsy is the hallmark of patients with CDKL5 mutation." (PMID 38874638, 2024). "Interestingly, a recent study using next-generation sequencing identified CDKL5 as a gene that is potentially involved in cardiac disorders associated with epilepsy, suggesting that CDKL5 may play a role in cardiac function." (PMID 36982627, 2023).
epilepsy (continued). "We aim to describe current treatment approaches and emerging therapies for epilepsy and additional treatable neurological symptoms (sleep dysfunction, behavioral dysregulation, movement disorders, and swallowing dysfunction) in individuals with CDKL5 deficiency disorder at experienced centers." (PMID 34530725, 2021). "A study by our group that included 20 epilepsy patients with personal or family history of heart rhythm disturbance/cardiac arrhythmia/sudden death identified four missense variants in epilepsy genes CDKL5, CNTNAP2, GRIN2A, and ADGRV1, with complete segregation within the family." (PMID 31018519, 2019). "The median age of epilepsy onset was much earlier in females with the CDKL5 disorder (6.0 weeks) than Rett syndrome (4.9 years) and the risk of developing seizures was much greater in CDKL5 affected females (log rank test p <0.001) during the observation period." (PMID 27080038, 2016). "Cyclin-Dependent Kinase-Like 5 (CDKL5) Deficiency Disorder (CDD) is a rare genetic condition characterized by early-onset, pharmacoresistant epilepsy and severe global developmental delay." (PMID 42261526, 2026). "Even orphan drugs for rare diseases have been commercialized for individualized pharmacological approaches, such as Fenfluramine and Cannabidiol for Dravet syndrome and Lennox–Gastaut syndrome, or ganaxolone for CDKL5-mediated epilepsies." (PMID 40283547, 2025). "Given that CDKL5-related epilepsy often evolves into an LGS-like presentation, this subgroup analysis is clinically relevant." (PMID 40944069, 2025). "To date, more than 500 genes have been identified in relation to epilepsy, including mutations in SCNA1, SCL2A1, KCNQ1, CDKL5, and DEPDC5." (PMID 40283547, 2025). "With regard to EEG features, Buoni and colleagues studied the electro-clinical pattern of epilepsy in three CDKL5 patients." (PMID 38612920, 2024). "The cerebral cortex is a brain region severely and commonly affected in genetic neurological disorders, including epilepsy, and is a brain region where CDKL5 is highly expressed." (PMID 39409097, 2024). "The overall estimated annual incidence of single-gene epilepsies in this population was 1 per 2120 live births (47.2/100 000; 95% CI 36.9 to 57.5), with pathogenic variants in SCN1A, PCDH19, CDKL5 and KCNQ2, having the highest incidence for DEE." (PMID 39613335, 2024). "Zebrafish represent a valuable preclinical tool, with several available CDKL5 epilepsy models, potential for high-throughput screening, and a positive response to cannabinoids." (PMID 39409097, 2024). "One retrospective single-arm meta-analysis showed the effectiveness of the KD in children with cyclin-dependent kinase-like 5 (CDKL5)-related epilepsy, with the responder rate of 18%." (PMID 38732505, 2024). "Weak evidence showed that KDs were effective in the treatment of pediatric seizures, adult intractable epilepsy, drug-resistant epilepsy, and CDKL5-related epilepsy." (PMID 37836444, 2023). "Given the high epilepsy incidence in human CDKL5 and CACNA1E DEE patients, we investigated potential seizures." (PMID 38081835, 2023). "This paradox highlights a big gap in our understanding of CDKL5 function: early developmental onset of medically resistant epilepsy in CDD contrasts with a complete lack in experimental models." (PMID 37490324, 2023).